RNU2-34P (RNA, U2 small nuclear 34, pseudogene)
Gene: Small nuclear RNA gene on chromosome 4 (182,548,659 to 182,548,779, forward strand). Ensembl gene ENSG00000252343.
Homologues: Orthologues: macaque U2 (66% identical), chimpanzee U2 (50% identical), rabbit U2 (47% identical), zebrafish U2 (32% identical). Paralogues in human: RNU2-28P (56% identical), RNU2-42P (55% identical), RNU2-58P (55% identical), RNU2-12P (54% identical), U2 (54% identical), RNU2-10P (53% identical), RNU2-22P (53% identical), RNU2-41P (51% identical), RNU2-53P (51% identical), RNU2-35P (50% identical), RNU2-24P (50% identical), RNU2-72P (50% identical), and 63 more.